NGB (neuroglobin)
Diseases named in the same sentence as NGB in open-access papers (continued):
Sharing a sentence is not in itself a finding about the gene and the disease.
neurological disorders (10 papers, 2010 to 2025). "Our objective was to determine whether neuroglobin overexpression can be used to treat neurological disorders." (PMID 38796706, 2024). "Consequently, researchers worldwide are considering NGB upregulation or even its targeted delivery for treating neurological disorders given the concurring evidence of NGB induction upon several pathologies or cellular insults." (PMID 38796706, 2024). "The role of NGB in neurological diseases and nervous system tumors has been reported extensively." (PMID 37005662, 2023). "Many of its protective effects are mediated through steroid receptors and may also be related to neuroglobin, whose elevated levels have been shown to protect against neurological diseases." (PMID 37509151, 2023). "Finally, the possible contribution of the estrogenic regulation of neuroglobin to the generation of sex differences in brain pathology and the potential application of neuroglobin as therapy against neurological diseases will be examined." (PMID 34440676, 2021). "Neuroglobin is a specific oxygen-binding globin protein first discovered in 2000 that has been verified to play an endogenous neuroprotective molecule against ischemia, hypoxia, oxidative stress damage, and related neurological disorders." (PMID 31191229, 2019). "Neuroglobin emerges as a critical player that regulates immediate post-mitochondrial events in the intrinsic pathway of apoptosis, opening new avenues for therapeutic interventions in numerous neurological disorders." (PMID 20640154, 2010). "Thus, NGB may serve as a promising candidate for the treatment of neurological diseases." (PMID 40867117, 2025). "Thus, overexpressed NGB represents a critical player to counteract nerve cell death and the search for drugs and therapeutic strategies targeting NGB overexpression can open significant new opportunities to manage a wide number of very impacting neurological disorders." (PMID 27809238, 2016). "There had been some literature reports on NGB in neurological diseases and non-neurological tumors." (PMID 37005662, 2023).
neurodegenerative disease (7 papers, 2016 to 2023). A disorder of the central nervous system characterized by gradual and progressive loss of neural tissue and neurologic function. "The overexpression of NGB can protect neurons from mitochondrial dysfunction and neurodegenerative diseases such as AD." (PMID 37965040, 2023). "Altogether our data show that NGB expression is regulated by ERα binding on genomic regulatory regions supporting hormone therapy applications for the neuroprotection against neurodegenerative diseases." (PMID 27313512, 2016). "Of note, the different modulation of NGB levels triggered by Res in the presence of the two different ER subtypes (and present data) open a novel avenue in the field of pharmacological treatment of degenerative diseases." (PMID 36982977, 2023). "In conclusion, Res appears to be a promising molecule capable of maintaining high levels of NGB in neuronal-derived cells, leading to protection against oxidative stress and finding a therapeutic application for this molecule against pathological conditions such as neurodegenerative diseases." (PMID 36982977, 2023).
infection (5 papers, 2019 to 2026). The state of being infected such as from the introduction of a foreign agent such as serum, vaccine, antigenic substance or organism. "Together, we highlight the increasing relevance of PBP4 as a mediator of NGB resistance and discuss its potential as an important factor during infection diagnosis and therapy." (PMID 42075313, 2026).
mitochondrial disease (1 paper, 2024). "Our previous studies have demonstrated NGB capacity to protect visual function in Hq mice, which is a model of primary mitochondrial disease." (PMID 38796706, 2024).
retinopathy (1 paper, 2024). "We explored DNA methylation levels at chr14:77736811 (NGB) and chr14:57265055 (OTX2) in 9 T2D retinopathy cases and 66 T2D retinopathy controls, selected from the TwinsUK discovery and replication T2D cases." (PMID 38574408, 2024).
NGB also shares sentences with these, for which no sentence is quoted: gastric cancer (3 papers); cardiovascular disease (2); chronic gastritis (2); dementia (2); diabetes (2); endothelial dysfunction (2); urethritis (2); Anxiety (1); brain injury (1); cerebral malaria (1); co-infection (1); colitis (1); colon tumor (1); Crohn disease (1); hemorrhage (1); high blood pressure (1); infarct (1); injury (1); insomnia (1); invasive ductal carcinoma (1); liver cirrhosis (1); Liver Diseases (1); Obesity (1); obstructive sleep apnea (1); periodontitis (1); primary aldosteronism (1); retinal degeneration (1); sarcoma (1); thalassemia (1); thyroid tumor (1).
A further 1 disease shares a sentence with NGB in 1 paper.